FAM194C (family with sequence similarity 149 member C)
Synonyms: C3orf20; DKFZP434N1817
Tractability: Antibody: UniProt predicts a signal peptide or a membrane-spanning region.
Gene: Protein-coding gene on chromosome 3 (14,675,141 to 14,773,036, forward strand). Ensembl gene ENSG00000131379.
Subcellular location: Membrane
Subcellular location (Human Protein Atlas): Cytosol; Plasma membrane
Gene Ontology:
Molecular function: protein binding
Cellular component: cytoplasm; membrane
Genetic constraint (gnomAD): Loss-of-function variants: 77 observed, 93.54 expected, observed/expected ratio (o/e) 0.82, 90% interval 0.68 to 1. The upper end of that interval is the gene's LOEUF score, 1, which puts it in group 4 of 6, group 1 being the genes least tolerant of losing a copy. Missense variants: 1,056 observed, 1,180.9 expected, observed/expected ratio (o/e) 0.89, 90% interval 0.85 to 0.94. Synonymous variants: 436 observed, 462.3 expected, observed/expected ratio (o/e) 0.94, 90% interval 0.87 to 1.02.
Homologues: Orthologues: chimpanzee C3H3orf20 (99% identical), macaque C2H3orf20 (94% identical), dog C3orf20 (71% identical), rat C4h3orf20 (64% identical), mouse 4930590J08Rik (64% identical), guinea pig C3orf20 (62% identical). Paralogues in human: ERICH6 (9% identical), ERICH6B (7% identical).
Diseases named in the same sentence as FAM194C in open-access papers:
FAM194C is named in the same sentence as 10 diseases in open-access papers, as found by Europe PMC text mining. Sharing a sentence is not in itself a finding about the gene and the disease.
FAM194C shares sentences with these, for which no sentence is quoted: depression (1 paper); Intellectual disability (1); lymphoma (1); neuromyelitis optica (1); pancreatitis (1); Parkinson disease (1); precursor cell lymphoblastic leukemia (1); rheumatoid arthritis (1); schizophrenia (1); Sjogren syndrome (1).